SOS1 (SOS Ras/Rac guanine nucleotide exchange factor 1)
Diseases named in the same sentence as SOS1 in open-access papers (continued):
Sharing a sentence is not in itself a finding about the gene and the disease.
hypertrophic cardiomyopathy (2 papers, 2019 to 2022). A condition in which the myocardium is hypertrophied without an obvious cause. "For example, hypertrophic cardiomyopathy development during childhood can be triggered by genetic mutations in PTPN11, KRAS, Son of sevenless homolog 1 (SOS1), a RAS effector (RAF1), genes which are also involved in cancer developments." (PMID 35911555, 2022).
IgA nephropathy (2 papers, 2020 to 2024). "These three genes haven’t been directly associated with CKD but were implicated in IgA nephropathy (SOS1), diabetic kidney disease (MYLK), and paroxysmal nocturnal hemoglobinuria, respectively (PLCG1)." (PMID 32957963, 2020). "Metabolomics and proteomics have shown that SOS1 can serve as a potential biomarker for early IgA nephropathy and is involved in the regulation of immune system activation in IgA patients." (PMID 38632288, 2024).
ptosis (2 papers, 2018 to 2025). The drooping of the upper eyelid. "In the NS patients due to a SOS1 mutation, the most frequent ocular findings were hypertelorism and ptosis." (PMID 29948256, 2018).
skin papilloma (2 papers, 2021). A benign papillary neoplastic growth on the skin composed of epithelial cells and a fibrous stalk. "In this regard, it was also shown that SOS1 upregulation resulted in development of skin papillomas with 100% penetrance, supporting a critical role of SOS in this process in epidermal cells." (PMID 34205562, 2021).
(CMMRD) syndrome (1 paper, 2022).
adenoma (1 paper, 2024). A neoplasm arising from the epithelium. "This mainly concerns the MAP kinase signalling pathway starting with an increased expression of SOS1/2, which is higher in adenoma than in CRC." (PMID 38397199, 2024).
alexithymia (1 paper, 2022). An agnosia that is a deficiency in understanding, processing, or describing emotions. "Alexithymia and internalizing problems were more frequent in patients with variants in PTPN11 and SOS1, while PTPN11 patients also showed higher levels of externalizing problems." (PMID 36012976, 2022). "Regarding psychopathology, the findings largely confirmed our hypotheses, insofar as alexithymia was significantly present in two groups, PTPN11 and SOS1, while it was credibly present in PTPN11/NSML, SHOC2, CBL, and SOS2 as well." (PMID 36012976, 2022).
autism (1 paper, 2020). Persistent deficits in social interaction and communication and interaction as well as a markedly restricted repertoire of activity and interest as well as repetitive patterns of behavior. "Three children (21%) with a SOS1 gene mutation developed late onset feeding problems, one due to delayed gastric emptying, 1 because of an eating aversion caused by autism and 1 child due to a bad condition caused by heart disease." (PMID 32394265, 2020).
bleeding disorders (1 paper, 2021). "The mutational spectrum of patients with bleeding disorders was largely overlapping with that of the NS general population, including mutations in PTPN11, SOS1, RIT1, BRAF, and MAP2K1 genes." (PMID 34857025, 2021).
breast disease (1 paper, 2020). "We also analyzed the expression of AnxA6, GRF2, SOS1 and Ki67 by immunohistochemistry (IHC) in a breast disease spectrum and following chemotherapy." (PMID 32298357, 2020).
cartilage tumors (1 paper, 2021). "In addition, CD4-Cre-mediated conditional Sos1/2 or Erk1/2 deletion in chondrocytes resulted in cartilage tumors, which was similar to the cartilage tumors in wrist bones of 6-month-old CD4-CKO mice." (PMID 34764263, 2021).
cervical cancer (1 paper, 2025). A primary or metastatic malignant neoplasm involving the cervix. "Another research has shown that HOXC cluster antisense RNA 3 (HOXC-AS3) and up-regulating Sevenless Homolog 1 (SOS1) increases cervical cancer cell proliferation, migration and invasion by enhancement of the ErbB signalling pathway." (PMID 40028476, 2025).
congenital cardiomyopathy (1 paper, 2022). "However, it attempted to determine other genotype–phenotype correlations, such as the definitive association of mutations of PTPN11 and the presence of craniofacial anomalies, and the incidence of congenital cardiomyopathy with SOS1 mutations." (PMID 36291422, 2022).
Cryptozoospermia (1 paper, 2024). A type of oligozoospermia in which spermatozoa can be detected in an ejaculate only after centrifugation and inspection of the pellet. "We recently reported an infertile man with bilateral CR and cryptozoospermia carrying a pathogenic variant in SOS1 and proposed genetic alterations in the Ras/MAPK pathway as a novel etiology implicated in congenital CR and SPGF." (PMID 38654924, 2024). "Both SPGF patients with novel SOS1 variants had CR and cryptozoospermia." (PMID 38654924, 2024).
dyslipidemia (1 paper, 2017). "It is worth bearing in mind that all patients are similarly affected by dyslipidemia; therefore, it is reasonable to infer that the presence of T2D in the G1 + G2 groups could have an additive effect for the higher expression of SOS1 in comparison to the G3 normoglycemic patients." (PMID 28812028, 2017).
endometrial cancer (1 paper, 2016). Primary or metastatic malignant neoplasm involving the endometrium (mucous membrane that lines the endometrial cavity). "CD4, EPO, SOS1 and IFNA1 are related to several cellular mechanisms such as hematopoietic cell lineage determination, gonadotropin-releasing hormone (GnRH) signaling, cytokine-cytokine receptor interactions and endometrial cancer." (PMID 27832168, 2016).
energy metabolism disorders (1 paper, 2022). "The expression of SOS1 can affect intracellular ROS levels, and the loss of SOS1 leads to specific changes in mitochondrial shape, mass, and dynamics, resulting in energy metabolism disorders." (PMID 36572849, 2022).
giant cell tumor (1 paper, 2022). A benign, intermediate, or malignant tumor that arises from the bone or soft tissue. "We also recognized 2 patients (6%) with benign, non-cancerous, tumors: both patients had giant-cell tumors (affecting the left tibia and the nerve sheath of the first finger of the right hand, respectively); in the respective cases, PTPN11 and SOS1 mutations were identified." (PMID 36566191, 2022).
gingival tumor (1 paper, 2023). "Compared with normal gingival tissue, the expression of SOS1 in gingival tumors from the proband was abnormally increased, whereas no variants in SOS1 gene were found in all patients of the family." (PMID 37752101, 2023). "The ChIP-qPCR and electrophoresis of NHGFs and patient gingival tumor fibroblasts confirmed that ZNF513 in these cells had clear binding at the enrichment peak of the SOS1 promoter region, and the binding sequence was confirmed to be the genomic sequence of SOS1." (PMID 37752101, 2023).
granular cell tumors of the skin (1 paper, 2011). "We observed the occurrence of multiple tumors (i.e., MGCLs, abdominal rhabdomyosarcoma, cerebral glioma, and granular cell tumors of the skin) in one of the SOS1 mutation-positive subjects included in the study." (PMID 21387466, 2011).
Hernia (1 paper, 2020). "Together, our results show that PIK3R1, PTPN11, TGFBR1, CDC42, and SOS1 are probably the most essential proteins involved in human hernia formation." (PMID 31910207, 2020).
herpesvirus infection (1 paper, 2019). "Notably, GRB2 as well as SOS1 are regulated by non-coding RNAs in other g-herpesvirus infection systems, suggesting this may be a common strategy employed by g-herpesviruses to manipulate RTK signaling." (PMID 30615681, 2019).
Hirsutism (1 paper, 2021). Abnormally increased hair growth referring to a male pattern of body hair (androgenic hair). "In addition, fibroblasts isolated from the skin of patients with hirsutism show increased levels of Sos1 expression." (PMID 33946974, 2021).
Hypertelorism (1 paper, 2025). Interpupillary distance more than 2 SD above the mean (alternatively, the appearance of an increased interpupillary distance or widely spaced eyes). "Among them, mice with a deficiency for Fgfr1, Fgfr2, Kif3a, Kras, Ptch1, Rreb1, Sos1, and Tfap2a show excessive proliferation during midfacial development, resulting in hypertelorism, suggesting that mimics of miR-383-3p and miR-6951-3p activate cell proliferation through suppression of these genes." (PMID 40787625, 2025).
Inguinal hernia (1 paper, 2020). Protrusion of the contents of the abdominal cavity through the inguinal canal. "We discovered that PIK3R1, PTPN11, TGFBR1, CDC42, SOS1, and KRAS were the most essential inguinal hernia-causative proteins and UBC, GRB2, CTNNB1, HSP90AA1, CBL, PLCG1, and CRK were listed as the most commonly-involved downstream proteins." (PMID 31910207, 2020). "Thus, proteins PIK3R1, CDC42, TGFBR1, PTPN11, UBC, CTFR, and SOS1 may play an important role in the inguinal hernia PPI network." (PMID 31910207, 2020). "Five essential proteins (PIK3R1, PTPN11, TGFBR1, CDC42, and SOS1) and three downstream common proteins (UBC, GRB2, and CTNNB1) were found to be related to inguinal hernia development." (PMID 31910207, 2020). "Additionally, others also show that inguinal hernia-related essential proteins, PTPN11, CDC42, and SOS1 regulate the RAS/MAPK signaling pathway, which is another downstream effector of RTKs." (PMID 31910207, 2020).
Intellectual disability (1 paper, 2015). "This cluster comprises of a selection of genes that have been associated previously with intellectual disability, such as YWHAE, SOS1, and MAP2K2, and several whose function makes them likely candidates for involvement in ID." (PMID 25781962, 2015).
intrauterine growth restriction (1 paper, 2026). "Our data confirm a mild but consistent intrauterine growth restriction, particularly in children with PTPN11 or SOS1 variants." (PMID 41577878, 2026).
macrosomia (1 paper, 2011). "The analysis of distribution of the major clinical features among SOS1 mutation-positive subjects documented a significantly higher prevalence of fetal macrosomia in subjects with class 1B mutations compared to individuals with class 1A mutations (Fisher's exact probability = 0.024)." (PMID 21387466, 2011).
metastatic tumors (1 paper, 2020). "Given that Ki67 is a marker for cell growth, and that GRF2 and SOS1 promote cell growth via activation of Ras proteins, the increased expression of these proteins in malignant breast and metastatic tumors is consistent with the relatively rapid growth of these tumors compared to normal tissue." (PMID 32298357, 2020).
mucosal neuroma syndrome (1 paper, 2025). "Genetic testing revealed a SOS1 gene mutation without a RET mutation, leading to a provisional diagnosis of pure mucosal neuroma syndrome, a variant of MEN2B." (PMID 40075889, 2025).
Osteochondroma (1 paper, 2017). A common, benign cartiliginous neoplasm arising from the metaphysis of bone. "Interestingly, deletion of Sos1/2 via CD4cre also caused development of osteochondromas similar to DKOCD4 mice." (PMID 28507546, 2017). "Deletion of Sos1/2 reduces ERK activation, and deletion of either of these genes via CD4cre results in spontaneous osteochondroma formation." (PMID 28507546, 2017).
papilloma (1 paper, 2021). A benign epithelial neoplasm that projects above the surrounding epithelial surface and consists of villous or arborescent outgrowths of fibrovascular stroma. "In addition, SOS1 disruption (but not SOS2 ablation) delayed the onset of tumor initiation, decreased tumor growth, and prevented malignant progression of papillomas when using the known DMBA/TPA model of chemically induced skin carcinogenesis in mice." (PMID 34205562, 2021).
Peri-Implantitis (1 paper, 2019). An inflammatory process with loss of supporting bone in the tissues surrounding functioning DENTAL IMPLANTS. "In peri-implantitis, while SOS1 was previously identified as a hub gene but experimental evidence is similarly lacking." (PMID 31275749, 2019). "Three common leader genes; PSMD10, SOS1, and WASF3, were identified from the gene clusters linked to peri-implantitis and T2DM each." (PMID 31275749, 2019). "Three leader genes (PSMD10, SOS1, WASF3), eight cross-talk genes (PSMD10, PSMD6, EIF2S1, GSTP1, DNAJC3, SEC61A1, MAPT, and NME1), and one signaling pathway (IL-17 signaling) emerged as peri-implantitis and T2DM linkage mechanisms." (PMID 31275749, 2019).
periodontitis (1 paper, 2025). An acute or chronic inflammatory process that affects the tissues that surround and support the teeth. "In the Periodontitis group, the most significant genes included CTTNBP2NL, SOS1, RNF213, and IL12RB2." (PMID 40458179, 2025).
pleomorphic rhabdomyosarcoma (1 paper, 2025). An aggressive malignant mesenchymal neoplasm with skeletal muscle differentiation, occurring in adults and rarely in children. "One two-year-old girl carrying the SOS1 variant, presenting with vaginal bleeding, was diagnosed with uterine embryonal pleomorphic rhabdomyosarcoma and, at the time of the article, is undergoing chemotherapy." (PMID 40332000, 2025).
prostate tumors (1 paper, 2014). "Interestingly, in the African American derived MDA-PCa-2b, we observed significant decreases in ABCD3 and SOS1, which have been previously reported to be associated with African American prostate tumors." (PMID 25004396, 2014).
pulmonary valve dysplasia (1 paper, 2022). "Patients with mutations in SOS1 had pulmonary valve dysplasia with stenosis, biventricular hypertrophy and ASD." (PMID 35770001, 2022). "Other than pulmonary valve stenosis, SOS1 was associated with pulmonary valve dysplasia, biventricular hypertrophy and ASD in our study." (PMID 35770001, 2022).
pulmonary valve stenosis (1 paper, 2022). The pathologic narrowing of the orifice of the pulmonary valve. "SOS1 mutations most often result in pulmonary valve stenosis, much like PTPN11 mutations." (PMID 35770001, 2022). "SOS1, RIT1, PTPN11, and SOS2 mutations showed common cardiac abnormalities such as pulmonary valve stenosis." (PMID 35770001, 2022). "Among all the pathogenic variants, we found that patients with mutations in RIT1, SOS1, PTPN11, and SOS2 had common echocardiography figures characterized by pulmonary valve stenosis, while RAF1 patients had HCM." (PMID 35770001, 2022). "RIT1, SOS1, PTPN11, and SOS2 had common echocardiography features characterized by pulmonary valve stenosis, while RAF1 was characterized by HCM." (PMID 35770001, 2022).
sarcoma (1 paper, 2019). A usually aggressive malignant neoplasm of the soft tissue or bone. "SOS1 (SOS Ras/Rac guanine nucleotide exchange factor 1) regulates Rat sarcoma proteins and facilitates exchange of GTP for GDP." (PMID 31275749, 2019).
Stroke (1 paper, 2023). Sudden impairment of blood flow to a part of the brain due to occlusion or rupture of an artery to the brain. "Knocking out circ-Memo1 in hypoxia/reoxygenation(H/R)-treated HBMVECs cells increased the expression level of miR-17–5p and decreased the activity of SOS1, reducing oxidative stress and cell damage after stroke and improving cell viability." (PMID 38203348, 2023). "SOS1 could promote the phosphorylation of extracellular signal-regulating kinases 1/2 (ERK1/2) and activate the ERK/nuclear factor-κB (NF-κB) signaling pathway, which aggravates oxidative stress after stroke." (PMID 38203348, 2023).
testicular cancer (1 paper, 2024). A primary or metastatic malignant neoplasm that affects the testis. "The patient with SOS1 p.Q214H had been diagnosed with testicular cancer." (PMID 38654924, 2024).
thyroid tumor (1 paper, 2021). A benign or malignant neoplasm affecting the thyroid gland. "SOS1 and SPOP have been previously found mutated in thyroid tumors negative for RAS and BRAF mutations and in several types of cancers such as prostate, lung, and colon." (PMID 34680332, 2021).
cancer (83 papers, 2012 to 2025). A tumor composed of atypical neoplastic, often pleomorphic cells that invade other tissues. "A SOS1-directed PROTAC (9d) was produced by linking a VHL ligand to the SOS1 agonist VUBI-1 that induced SOS1 degradation in various KRAS-mutated cancer cells with high antiproliferation activity." (PMID 38686056, 2024). "Small-molecule SOS1 inhibitors that disrupt the SOS1–RAS interaction have been under development for the treatment of KRAS-mutated cancers." (PMID 38338909, 2024). "In preclinical PDAC models, it has been shown that SOS1 is essential for the survival of RAS-mutated cancer cells." (PMID 38338909, 2024). "9d induced SOS1 degradation in various KRAS-mutated cancer cells and displayed higher antiproliferation activity compared to the parent SOS1 agonist." (PMID 38023987, 2023). "Combined MEK and SOS1 inhibition has also resulted in durable tumor regressions in KRAS mutation-driven cancer models." (PMID 37774394, 2023). "Genetic variants of unclear significance were however detected in genes such as CDH1, DICER1, MEN1, RET, CREBBP, RAD51C, or SOS1, which are linked to autosomal dominant predisposition to cancer." (PMID 35250968, 2022). "Here, the discovery of potent, orally available SHP2 and SOS1 inhibitors has the potential to dramatically augment oncogene-targeted therapies for RAS-mutated cancer." (PMID 33924994, 2021). "Here, we show marked synergy between vertical inhibition of EGFR and SOS1 in EGFR mutated cancer cells, but only under 3D culture conditions." (PMID 32897190, 2020). "SOS1 inhibitors are also under investigation for treating RAS-mutated cancers." (PMID 38982514, 2024). "The ability to pharmacologically manipulate the common proximal signaling intermediates SHP2 and SOS1/2 may lead to optimized therapeutic combinations that can be used to treat RAS-mutated cancers." (PMID 33924994, 2021). "We and others have shown that SOS1 and SOS2 may be important therapeutic targets in KRAS-mutated cancer cells, and a specific SOS1 inhibitor (BAY-293) has recently been identified." (PMID 32897190, 2020). "Similar to the findings in KRAS-mutant cancers, the proteasome inhibitor MG132 rescued the loss of SOS1 upon SIAIS562055 treatment." (PMID 39437162, 2025). "A preclinical study explores the development of novel Son of sevenless homolog 1 (SOS1) degraders using PROTAC technology to target KRAS‐driven cancers." (PMID 39898116, 2025). "It has also been reported that SOS1 PROTAC exhibits potent antitumor activity in KRAS-mutant cancers." (PMID 39437162, 2025). "SOS1 inhibition has shown promise in delaying cancer progression, highlighting its potential as a therapeutic target." (PMID 40226549, 2025). "Given the pivotal role of SOS1 in the progression of RAS-driven cancer, inhibiting the binding between SOS1 and RAS has emerged as a promising therapeutic avenue against RAS-driven tumours." (PMID 38665844, 2024). "SOS1 catalyzes the formation of KRAS-GTP complex to activate multiple downstream signaling pathways that trigger cancer cell proliferation." (PMID 38734764, 2024). "Preclinical evidence suggests that the inhibition of SOS1 attenuates feedback reactivation induced by MEK inhibitors in KRAS-dependent cancers improving sensitivity to MEK inhibitors." (PMID 38756650, 2024). "BAY-293, an SOS1 inhibitor exhibits synergistic activity when combined with ARS-1620 in KRASG12C mutant CRC cancer cell lines proving that targeting the inactive GDP-bound form is a promising approach for generating anti-RAS therapeutics." (PMID 38978742, 2024). "Raf1, B-Raf, EGFR, SOS1, Bad, Myc, Jun, and Mcl1 were mapped to pathways related to apoptosis or cancers." (PMID 38643189, 2024). "The oral small-molecule SOS1 inhibitor BI-3406 disrupts the SOS1–KRAS interaction for all KRAS alleles in vitro and in KRAS-dependent cancer models." (PMID 38686056, 2024).